INS (insulin)
Diseases named in the same sentence as INS in open-access papers (continued):
Sharing a sentence is not in itself a finding about the gene and the disease.
metabolic syndrome (continued). "At the same time, it significantly improved the glucose tolerance and insulin sensitivity of male adult offspring, reduced their body fat content, and ameliorated dyslipidemia." (PMID 35299765, 2022). "Anthracyline and taxane chemotherapies have been associated with modest gains in weight (1–3 kg) and adverse changes in glucose and insulin sensitivity and other markers of the metabolic syndrome in patients with early BC." (PMID 34912072, 2022). "This is evidenced by the ability of APE to alleviate glucose and insulin homeostasis, ameliorate metabolic derangement including dyslipidemia, hepatorenal dysfunction, and restore pancreatic oxidative stress and β‐cell function in the treated diabetic animals." (PMID 35432973, 2022). "Compared to the metabolic syndrome model group, the low-carbohydrates-high-fat-diet-fed group showed significantly lower body weight, BMI, glucose, insulin, and HIMA-IR." (PMID 35565871, 2022). "The leptin-deficient ob/ob mice and insulin-deficient T1DM mice were established to confirm that insulin and leptin are essential for APF anti-metabolic syndromes by regulating adipoinsular axis." (PMID 36046814, 2022). "Patients initiating SGLT2i early were younger, and less likely to be female and have dyslipidemia, hypertension, concurrent use of insulin, lipid lowering, antiplatelet, or oral hypoglycemic therapy, and more likely to have a shorter duration of T2D." (PMID 36331955, 2022). "FMT from donors of different body sizes shows varying degrees of insulin sensitivity in obese subjects with metabolic syndrome." (PMID 36590426, 2022). "Subjects were retrospectively grouped into MHO and MUO by the presence of metabolic syndrome and secondarily by estimates of insulin sensitivity (HOMA-IR and ISIClamp)." (PMID 35346256, 2022). "This study shows that physical activity can significantly lower insulin levels, and high-intensity physical activity still has additional potential benefits for insulin levels, even in the condition of dyslipidemia and hyperuricemia." (PMID 35185617, 2022). "A randomized controlled trial suggested that whole egg consumption further improved atherogenic lipoprotein profile and insulin sensitivity in individuals with metabolic syndrome compared with yolk-free egg substitute." (PMID 36429496, 2022). "Our results are consistent with previous findings on transient lean donor -9gut microbiota in patients with metabolic syndrome, which showed a significant improvement in peripheral insulin sensitivity at 6 weeks." (PMID 36704100, 2022). "In women with PCOS, metabolic syndrome and its individual components are prevalent, especially in women with the highest BMI and insulin levels." (PMID 36010645, 2022). "Clinical and metabolic evaluations were performed (BMI-SDS, insulin, and glucose at fasting and during an oral glucose tolerance test, lipid profile, blood pressure), and metabolic syndrome was detected." (PMID 36213269, 2022). "High triglycerides and low HDL-C are the characteristic types of dyslipidemia seen in insulin-resistant subjects." (PMID 35210633, 2022). "The insulin-mediated control of sterol-regulatory element binding protein expression in the liver and adipose tissue is central to alterations in lipid metabolism associated with hyperinsulinemia, over-activity of sterol-regulatory element binding protein signaling may lead to dyslipidemia." (PMID 36273126, 2022). "If implemented among rodents with metabolic syndrome, it induces increased insulin sensitivity and a reduction in abdominal fat, blood pressure, and inflammation." (PMID 35406122, 2022). "The results of the studies were combined with insulin sensitivity, insulin, resistance, glucose tolerance and metabolic syndrome." (PMID 35065638, 2022). "At twelve weeks, these taxa correlated positively with insulin, WI, diuresis and blood pressure, all of them related to the metabolic syndrome." (PMID 35972974, 2022).
metabolic syndrome (continued). "A previous study reported that consuming breakfast cereal containing 28% SDS+RS resulted in significantly lower postprandial glucose and insulin release, showing potential for improving metabolic syndrome." (PMID 35205970, 2022). "To validate metabolic syndrome, we evaluated body weight, insulin levels, oral glucose tolerance test (OGTT), and blood pressure parameters of the animals." (PMID 35379188, 2022). "T2DM is a multi-factor metabolic syndrome, mainly characterized by chronic hyperglycemia due to a reduced sensitivity to insulin and impaired insulin secretion, leading to multiple organ dysfunction." (PMID 38647883, 2022). "In T1D, greater fasting pro-NT associated with poor glycemic control at baseline and predicted increased waist circumference, reduced insulin sensitivity, dyslipidemia and hypertension at 10-year follow-up." (PMID 34455471, 2022). "Blautia coccoides seem to counter the abnormal glucose and insulin homeostasis in patients with metabolic syndrome by producing butyrate that contributes to maintaining normal blood glucose levels." (PMID 35208888, 2022). "The obtained data are strongly related to our previous findings that showed that calystegines mitigate oxidative stress in equine ASCs affected by metabolic syndrome and therefore increase their sensitivity to insulin." (PMID 35327652, 2022). "Variables that had a value of standardized difference > 10% were age, dyslipidemia, nephropathy, eye diseases, diabetic polyneuropathy, stroke, insulin, meglitinide, acarbose, calcium channel blockers, statins, fibrates, heart failure and liver cirrhosis." (PMID 36277720, 2022). "We investigated the association between dietary insulin index (DII) and dietary insulin load (DIL), and metabolic syndrome (MetS) risk." (PMID 36585722, 2022). "On the other hand, reducing body weight contributes to lower circulating androgen and insulin levels, ameliorates ovulatory and menstrual aberrations, and improves dyslipidemia." (PMID 36611967, 2022). "Serum levels of insulin were significantly higher in patients with metabolic syndrome (56.14 ± 6.75) than in normal controls (10.91 ± 2.12)." (PMID 35736651, 2022). "It is known that resistance to insulin, which leads to lowered effects on glucose and lipid metabolism, affects the prevalence of metabolic syndrome considerably." (PMID 36013484, 2022). "As we have previously demonstrated HFHS dams display glucose intolerance specific to pregnancy, decreased serum insulin levels and beta cell numbers, dyslipidemia, and long-term maternal health complications." (PMID 36520818, 2022). "In closing, we confirm that metformin improves metabolic insulin sensitivity in subjects with metabolic syndrome and provide the first evidence that it also improves, without normalizing, muscle microvascular insulin sensitivity." (PMID 34957859, 2022). "Subjects with endogenous Cushing syndrome and the metabolic syndrome differ significantly with respect to insulin secretion." (PMID 35897752, 2022). "This is because compared with people with normal BMI, overweight and obese people are more likely to have metabolic syndrome, such as fat metabolism disorder and insulin antibody, which leads to the occurrence of cardiovascular diseases such as hypertension." (PMID 35042940, 2022). "These include metabolic syndrome and insulin signaling (case study 1) and chemicals that affect the cardiovascular system (case study 2)." (PMID 34418449, 2022). "The results showed that the growth factor pathway, signal transduction mechanism, and dyslipidemia of insulin were related to the pathogenesis of PRAD." (PMID 36284990, 2022). "For example, overactivation of the RAAS and insulin resistance alter systemic lipid metabolism, leading to the development of atherogenic dyslipidemia." (PMID 36589440, 2022). "Metabolic syndrome (ATP-III diagnostic criteria) was diagnosed in 51.7% of cases; 61.2% were insulin resistant, and 71.2% presented hepatic steatosis (US assessment)." (PMID 35956387, 2022).
metabolic syndrome (continued). "This study systematically reviewed the relevant clinical trials to evaluate the effects of intermittent fasting diet on glucose and lipid metabolism and insulin sensitivity in patients with metabolic syndrome." (PMID 35371260, 2022). "Modern studies have provided more color to the connection between overnutrition and diseases, variously described as under the umbrella of metabolic syndrome, which are all characterized by the reduced ability (resistance) of insulin to lower blood glucose." (PMID 34863942, 2022). "Unlike the other fatty liver indices studied here, NAFLD-FLS does not include body weight and considers metabolic parameters, including insulin and metabolic syndrome." (PMID 36145146, 2022). "Data on anthropometric measurements, clinical components of metabolic syndrome and fasting serum insulin were collected." (PMID 36589844, 2022). "Confirming the results of between-group comparisons, sex, BMI SDS, TG, insulin, HOMA-IR, APRI, uric acid and metabolic syndrome were significantly associated with NAFLD, while age, WC, T-C, HDL-C, LDL-C, glucose total bilirubin, DBP and SBP were not." (PMID 35208229, 2022). "Previous experiments using FMT to interfere with metabolic syndrome showed that FMT improved insulin sensitivity, increased gut microbial diversity, and significantly increased butyric acid producing bacteria in patients with metabolic syndrome." (PMID 36704100, 2022). "These metabolic processes are also expressed in control pregnant subjects since pregnancy is characterized by para-physiological dyslipidemia and insulin resistance." (PMID 36235696, 2022). "In another study that evaluated the effects of FMT on 26 patients with metabolic syndrome, 65% of them showed improved insulin sensitivity 6 weeks after treatment, an effect associated with Bifidobacterium-induced increases in acetate." (PMID 36569149, 2022). "Participants with higher TyG had more frequent dyslipidemia and hypertension, and higher levels of BMI, fasting glucose, fasting insulin, and triglyceride (P < 0.05)." (PMID 36221073, 2022). "Herein, J-12 improved dyslipidemia, insulin and leptin resistance, activated adiponectin, and reduced pancreatic and hepatic tissue damage in rats with HIP." (PMID 36615827, 2022). "This research group have reported that an energy-restricted diet enriched with ALA was accompanied by a significant decrease in body weight, systolic blood pressure, dyslipidemia, insulin sensitivity, inflammation, and endothelial function parameters." (PMID 35889342, 2022). "One study from China on a very small number of cases showed that insulin treatment in GCK(+) newborns led to significantly lower weight babies with significantly higher rates of dyslipidemia at adulthood." (PMID 35627517, 2022). "Six weeks after the infusion of the gut microbiota from lean donors to male recipients with metabolic syndrome, the levels of butyrate-producing intestinal microbiota and the insulin sensitivity of the recipients were significantly increased." (PMID 35008906, 2022). "The serum DPP-4 levels were positively correlated with adipocyte size and metabolic-syndrome indices, such as BMI, insulin, and leptin, and negatively correlated with age and adiponectin levels." (PMID 35893426, 2022). "Increased levels of sDPP4 have also been detected in metabolic syndrome, where sDPP4 positively correlated with various parameters such as body mass index, adipocyte surface, and leptin and insulin levels." (PMID 36009573, 2022). "Among adults with the metabolic syndrome, PAB, one betainized compounds, was associated with favorable fasting insulin, lipid profiles and inflammation." (PMID 35832425, 2022). "Therefore, selenoproteins have an important role in insulin resistance (IR) and metabolic syndrome (MetS) generation, modulating the reactive oxygen species (ROS) implicated in insulin signaling and the energetic sensor AMP-activated protein kinase (AMPK)." (PMID 35204276, 2022).
metabolic syndrome (continued). "Patients with GD show a damaged, altered metabolism; GD has been described as a clinical phenotype of an accelerated metabolic syndrome characterized by anti-insulin effects and dyslipidemia." (PMID 35745231, 2022). "Conversely, microbial acetate elevated in the context of a high-fat diet promotes metabolic syndrome by activating the parasympathetic nervous system to stimulate ghrelin and insulin secretion." (PMID 35276770, 2022). "N-3 PUFA phospholipids improve metabolic syndrome by altering liver gene expression, accelerating fatty acid metabolism, reducing inflammatory response, and enhancing insulin sensitivity." (PMID 36291067, 2022). "Collectively, these metabolic data indicate that CAMKK2 inhibition impacts symptoms of metabolic syndrome including sustained improvements in insulin sensitivity in preclinical models of prostate cancer." (PMID 35741020, 2022). "Collectively, we here profiled prophopreoteome features under two different insulin-resistant conditions with clinical relevance: inflammation and dyslipidemia." (PMID 35055191, 2022). "During normal pregnancy, plasma lipid mass spectra including TG, TC, HDL, and LDL levels change significantly due to insulin resistance, lipoprotein synthesis, and increased lipolysis in adipose tissue, which is called dyslipidemia during pregnancy (DLP)." (PMID 35285096, 2022). "A series of metabolic changes characterize the metabolic syndrome in late gestation, especially insulin resistance." (PMID 36407549, 2022). "This includes metabolic syndrome and insulin signaling (case study 1) and chemicals that impact the cardiovascular system (case study 2)." (PMID 34418449, 2022). "Eleven studies investigated the relationship between sedentary behavior and metabolic syndrome/cardiovascular disease risk factors (e.g., triglycerides, HDL cholesterol, glucose, insulin, and blood pressure)." (PMID 36011137, 2022). "The FXR agonist obeticholic acid (OCA) can normalize insulin sensitivity in visceral preadipocytes as well as improve liver function and adipose tissue function in rabbits with metabolic syndrome." (PMID 36091227, 2022). "Cross-sectional studies showed that acute phase reactants such as C-reactive protein (CRP) and cytokines (lL-6 and TNF-α) are related to components of the MS, such as BMI, WC, resistance to insulin, hypertension, and dyslipidemia." (PMID 34957175, 2021). "Women with POI have been reported to have several risk factors for the development of cardiovascular disease: endothelial dysfunction, autonomic dysfunction, abnormal lipid profile, insulin action disturbances, and metabolic syndrome." (PMID 33716979, 2021). "that found that infusion of microbiota from lean donors, increased insulin sensitivity in recipients with metabolic syndrome." (PMID 33936094, 2021). "Metabolism of VLDL in peripheral tissues is dependent on endothelial lipoprotein lipase, which has been shown to have reduced activity by insulin in metabolic syndrome." (PMID 34745660, 2021). "PPARα agonists, such as fenofibrate and bezafibrate, are widely used to treat dyslipidemia, preventing hepatic steatosis and improving insulin sensitivity." (PMID 34539442, 2021). "At routine low-dose exposure levels, exposure to endocrine disruptors affected metabolic-syndrome-related indicators, including insulin secretion, and was related to liver indices and sex hormone levels." (PMID 33677859, 2021). "Participants in case groups were patients with T2D or patients suffered from other glycemic disorders including impaired glucose tolerance (IGT), impaired insulin function and metabolic syndrome." (PMID 34215825, 2021). "During exploratory efforts to identify a potentially novel series of AMPK activators, we came across reports of fatty acid–derived molecules with hints of efficacy in preclinical models of dyslipidemia and insulin sensitization." (PMID 33724959, 2021).
metabolic syndrome (continued). "A recent study described that RA patients taking MTX were less prone to suffer metabolic syndrome, since they displayed an improvement in the insulin sensitivity through the increase of the insulin activity and the transport and metabolism of glucose." (PMID 34721412, 2021). "Routinely used insulin sensitizers metformin and pioglitazone, improved the glucose utilization and dyslipidemia in iNOS-/- mice along with rescued circulating LDL which was not affected by NO sufficiency." (PMID 35008623, 2021). "Logistic regression found that age, waist circumference, insulin, follicle-stimulating hormone, and sex hormone-binding globulin were independent predictors for dyslipidemia." (PMID 34977197, 2021). "This was based on the number of metabolic syndrome parameters present and an assessment of insulin sensitivity (using the Matsuda index score) and LGCSI as determined by hsCRP levels." (PMID 34943258, 2021). "Based on our experimental data, deuterium-depleted water can offer clinical benefits in the treatment of patients with metabolic syndrome by increasing insulin sensitivity." (PMID 34510301, 2021). "Transplantation of gut microbiota from lean donors to recipients with metabolic syndrome has been shown to increase levels of butyrate-producing microbiota and improve insulin sensitivity." (PMID 34737970, 2021). "Phascolarctobacterium is related to both insulin sensitivity and secretion, and a higher abundance of Phascolarctobacterium was observed in women with metabolic syndrome." (PMID 34257691, 2021). "Fecal microbiota transplants from lean donors to insulin-resistant individuals with metabolic syndrome have been shown to increase insulin sensitivity and the number of microbiota producing butyrate, an SCFA known to affect satiety hormones." (PMID 34007770, 2021). "In our study, HTG rats were characterized by dyslipidemia, leading to ectopic lipid accumulation, impaired glucose tolerance, and insulin resistance of peripheral tissue." (PMID 33467512, 2021). "The skeletal muscle accounts for 40-50% of the body weight and mediates 75% of insulin-stimulated glucose uptake, and is therefore one of the main potential targets for the treatment of metabolic syndrome, diabetes, and many other disorders." (PMID 34082690, 2021). "To investigate the diagnostic value of resistin in horses, we studied three categories of animals: healthy controls, horses with inflammatory conditions, and horses with insulin dysregulation/metabolic syndrome." (PMID 35011183, 2021). "AA has also been shown to improve insulin sensitivity in Sprague-Dawley rats with metabolic syndrome." (PMID 34439409, 2021). "Here, we demonstrate the presence of alternatively spliced variants of sortilin in mouse 3T3L1 adipocytes and their differential expression in insulin resistant conditions, which underlie T2DM and metabolic syndrome." (PMID 33498179, 2021). "A human study showed that small intestinal infusions of feces from lean male donors to treatment-naïve individuals with metabolic syndrome increased the insulin sensitivity of the recipients, along with levels of butyrate-producing microbiota." (PMID 33869077, 2021). "There is a growing consensus that enhancing insulin sensitivity is an important therapeutic strategy for metabolic syndrome." (PMID 34122092, 2021). "Metabolic syndrome is characterized by the coexistence of different severe abnormalities, including hypertension, abdominal obesity, hyperlipidemia, and disorders in insulin signaling." (PMID 33946264, 2021). "One study examined the effects of lean donor versus self-FMT on metabolic syndrome patients and found that insulin sensitivity improves significantly at 6-weeks after FMT in male recipients with the metabolic syndrome." (PMID 33897618, 2021). "In a case study, a patient with T2DM, metabolic syndrome, and hypothyroidism was first treated with insulin followed by LT4." (PMID 34405550, 2021).